ZC4H2 (zinc finger C4H2-type containing)
Description:
Involved in the development of several major noradrenergic neuron populations, including the locus coeruleus. Involved in neuronal development and in neuromuscular junction formation. Binds Zn(2+) ion with high affinity. The RNF220/ZC4H2 complex monoubiquitinates PHOX2A and PHOX2B to enhance their DNA-binding ability and transactivity (By similarity).
Synonyms: HCA127; KIAA1166; MCS; MRXS4; WRWF; WRWFFR; WWS
Tractability: Antibody: UniProt places it where antibodies can reach, with high confidence; its Gene Ontology location is reachable by antibodies, with medium confidence. PROTAC: ubiquitination databases record sites on it.
Gene: Protein-coding gene on chromosome X (64,915,802 to 65,034,713, reverse strand). Ensembl gene ENSG00000126970.
Subcellular location: Cytoplasm; Nucleus; Postsynaptic cell membrane
Subcellular location (Human Protein Atlas): Microtubules; Primary cilium; Vesicles; Basal body
Gene Ontology:
Molecular function: protein binding
Biological process: nervous system development; positive regulation of neuron differentiation; positive regulation of transcription by RNA polymerase II; protein monoubiquitination; regulation of transcription regulatory region DNA binding; neuromuscular junction development; spinal cord motor neuron differentiation
Cellular component: cytoplasm; nucleus; postsynaptic membrane; protein-containing complex; neuronal cell body
Gene-disease validity (ClinGen):
ClinGen rates the evidence that ZC4H2 causes each of these diseases.
X-linked syndromic intellectual disability (X-linked): Definitive. A syndromic intellectual disability with an X-linked mode of inheritance.
Homologues: Orthologues: chimpanzee ZC4H2 (100% identical), dog ZC4H2 (100% identical), macaque ZC4H2 (100% identical), mouse Zc4h2 (100% identical), rabbit ZC4H2 (100% identical), rat Zc4h2 (100% identical), guinea pig Zc4h2 (99% identical), pig ZC4H2 (99% identical), tropical clawed frog zc4h2 (98% identical), zebrafish zc4h2 (94% identical), Drosophila melanogaster CG13001 (53% identical), Caenorhabditis elegans vab-23 (30% identical), and 1 more.
Diseases named in the same sentence as ZC4H2 in open-access papers:
ZC4H2 is named in the same sentence as 30 diseases in open-access papers, as found by Europe PMC text mining. Sharing a sentence is not in itself a finding about the gene and the disease. The quoted sentences say what the papers report.
Wieacker-Wolff syndrome (7 papers, 2020 to 2025). A severe X-linked recessive neurodevelopmental disorder characterized by severe contractures (arthrogryposis) and intellectual disability. "Wieacker-Wolff syndrome is a rare genetic cause of neuromuscular arthrogryposis, resulting from pathogenic variants in the ZC4H2 gene." (PMID 41322872, 2025). "Pathogenic variants in the ZC4H2 gene have been associated with Wieacker–Wolff syndrome, now called ZC4H2-related X-linked syndromic intellectual disability, or ZARD." (PMID 40276104, 2025). "Pathogenic ZC4H2 variants are associated with Wieacker-Wolff syndrome, an X-linked disorder with dominant or recessive inheritance." (PMID 41322872, 2025). "Prenatal imaging suggested caudal regression syndrome, whereas autopsy and genetic analyses confirmed Wieacker-Wolff syndrome due to a de novo ZC4H2 variant." (PMID 41322872, 2025). "ZC4H2 is associated with Wieacker–Wolff syndrome, characterized by the presence of foot contractures, muscle atrophy, and oculomotor apraxia." (PMID 34356068, 2021). "Interestingly, mutations in the X-linked ZC4H2 gene are the cause of so-called ZC4H2-associated rare disorders (ZARDs)), formerly referred to as Wieacker–Wolff syndrome or Miles–Carpenter syndrome." (PMID 32443528, 2020). "Comparable diagnostic difficulties have been reported in previously published cases of Wieacker-Wolff syndrome and other ZC4H2-related disorders." (PMID 41322872, 2025). "The CN+SNP array revealed a 95 kb deletion at Xq11.2 spanning exon 1 of the ZC4H2 gene (MIM# 300897), resulting in a certain diagnosis of X‐linked Wieacker‐Wolff syndrome (MIM# 314580)." (PMID 32730690, 2020).
Intellectual disability (6 papers, 2015 to 2025). "Intellectual disability was universally present in individuals with variants in ZC4H2 (5/5), DYNC1H1 (4/4), TOR1A (2/2), KAT6B (1/1), GLDN (1/1), and GPC3 (1/1), signifying a strong association between these genes and cognitive deficits." (PMID 40443119, 2025). "ZC4H2 is a small nuclear protein associated with intellectual disability and neural development in humans." (PMID 28814648, 2017). "This approach has proven instrumental in the identification of novel XLID genes, including one gene that was prioritized at the top of our list, ZC4H2; this gene was recently implicated in Arthrogryposis Multiplex Congenita and Intellectual Disability." (PMID 25679214, 2015). "Mutations of both RLIM and ZC4H2 were reported to be associated with human intellectual disability." (PMID 35040952, 2022). "In humans, mutations in ZC4H2, a zinc-finger nuclear factor, have been reported to cause various clinical phenotypes, including arthrogryposis multiplex congenita, intellectual disability, epilepsy, spasticity, hypotonia, etc., which are now referred to as ZC4H2-associated rare disorders (ZARD)." (PMID 32630355, 2020). "Cognitive involvement, including individuals with intellectual disability and/or autism spectrum disorder, was observed in 27% of cases (27/100), mostly associated with pathogenic variants in DYNC1H1, TOR1A, and ZC4H2." (PMID 40443119, 2025). "The observation of specific genotype–phenotype correlations, such as the increased association of intellectual disability with variants in DYNC1H1, ZC4H2, and TOR1A, is valuable for early prognosis and family counseling." (PMID 40443119, 2025). "Pathogenic variants of ZC4H2 can cause a variety of phenotypes, including arthrogryposis multiplex congenita (AMC) with joint flexion contractures and fetal hypokinesia/akinesia, distal limb muscle atrophy, hypotonia, motor delays, intellectual disability, and progressive brain atrophy." (PMID 40276104, 2025). "Furthermore, we also provide evidence to suggest that the impaired Smads-stabilizing activity of ZC4H2 mutants found in patients with intellectual disability might contribute to the related disease progression." (PMID 28814648, 2017).
arthrogryposis (3 papers, 2021 to 2025). A rare, non-progressive congenital disorder characterized by multiple joint contractures which are present at birth. "Four cases with arthrogryposis were screened and categorized as neuromuscular abnormalities, and the diagnostic yield was 50% (2/4) with variants in KLHL40 (case 26) and ZC4H2 (case 91)." (PMID 34367232, 2021). "None of the individuals with arthrogryposis caused by pathogenic variants in COL6A1, RYR1, or ZC4H2 achieved independent walking." (PMID 40443119, 2025).
breast carcinoma (1 paper, 2021). "Of the remaining 12 genes, seven (A4GALT, C2ORF74, HRCT1, ZC4H2, ZNF512, ZNF655, and ZNF608) show similar relative expression profiles in large patient samples and other breast cancer cell lines thereby giving insight into predicted role of H3K4me3 mediated gene regulation via the miRNA-mRNA axis." (PMID 34261302, 2021).
distal arthrogryposis (1 paper, 2018). A muscle tissue disease characterized by congenital joint contractures of hand and feet. "Expression of several genes linked to motor neuronopathy and familiar amyotrophic lateral sclerosis (EPHA4, IGHMBP2, VAPB, BICD2, and DYNC1H1) or distal arthrogryposis (MYH8, ZC4H2, MUSK, RAPSN) were significantly upregulated or downregulated." (PMID 29727687, 2018).
osteoporosis (1 paper, 2024). A condition of reduced bone mass, with decreased cortical thickness and a decrease in the number and size of the trabeculae of cancellous bone (but normal chemical composition), resulting in increased fracture incidence. "We showed that ZC4H2 is expressed in different bone tissues, and loss of ZC4H2 reduces bone calcification and leads to an osteoporosis-like phenotype." (PMID 39336725, 2024).
genetic diseases (2 papers, 2022 to 2025). "Pathogenic variants of zinc finger C4H2-type containing (ZC4H2) on the X chromosome cause a group of genetic diseases termed ZC4H2-associated rare disorders (ZARD), including Wieacker-Wolff Syndrome (WRWF) and Female-restricted Wieacker-Wolff Syndrome (WRWFFR)." (PMID 36140726, 2022).
tumor (2 papers, 2022 to 2023). "Here, our findings demonstrated an upregulation of ZC4H2 expression in HCC tumor tissues, insinuating its potential involvement in accelerating HCC progression." (PMID 37287752, 2023). "In addition, our study shows that depletion of RLIM inhibits MB cell growth in vitro and tumor formation in vivo, at least partially, by stabilizing the ZC4H2/RNF220 complex." (PMID 35040952, 2022). "The qRT-PCR results revealed a significant upregulation of CBX2, SPP1, and ZC4H2, alongside a notable downregulation of FMO3 in tumor tissues." (PMID 37287752, 2023). "Significant disparities in protein expression levels of CBX2, SPP1, ZC4H2, and FMO3 were detected between tumor tissues and matched para-tumor tissues." (PMID 37287752, 2023).
infection (1 paper, 2022). The state of being infected such as from the introduction of a foreign agent such as serum, vaccine, antigenic substance or organism. "On day 10, after infection with ZC4H2-shRNA-1 or ZC4H2-shRNA-3, almost all of the NSCs had died; only one cluster of NSCs could be observed after infection with ZC4H2-shRNA-2, in which the expression levels of ZC4H2 were greater than half of that of the normal controls." (PMID 36140726, 2022).
malignant tumor (1 paper, 2023). "Furthermore, through functional enrichment analysis, we found a significant correlation between four signature genes (CBX2, LDHA, SPP1, and ZC4H2) and malignant tumor biology, exhibiting upregulation in high-risk patients." (PMID 37287752, 2023).
ZC4H2 also shares sentences with these, for which no sentence is quoted: arthrogryposis multiplex congenita (2 papers); scoliosis (2); Alzheimer disease (1); amyotrophic lateral sclerosis (1); autism spectrum disorder (1); bipolar disorder (1); caudal regression syndrome (1); cognitive deficits (1); colon cancer (1); dementia (1); early infantile epileptic encephalopathy (1); epilepsy (1); medulloblastoma (1); neurodegenerative disease (1); neuromuscular disease (1); neuronal ceroid lipofuscinosis (1); Oculomotor apraxia (1); prostate carcinoma (1); schizophrenia (1); X-linked syndromic intellectual disability (1).